OR2T34 (olfactory receptor family 2 subfamily T member 34)
Description:
Odorant receptor.
Tractability: Small molecule: it belongs to a druggable protein family. Antibody: UniProt places it where antibodies can reach, with medium confidence; UniProt predicts a signal peptide or a membrane-spanning region; its Gene Ontology location is reachable by antibodies, with medium confidence.
Gene: Protein-coding gene on chromosome 1 (248,573,801 to 248,574,757, reverse strand). Ensembl gene ENSG00000183310.
Subcellular location: Cell membrane
Pathways (Reactome):
Sensory Perception: Expression and translocation of olfactory receptors
Gene Ontology:
Molecular function: olfactory receptor activity; G protein-coupled receptor activity
Biological process: detection of chemical stimulus involved in sensory perception of smell; G protein-coupled receptor signaling pathway
Cellular component: plasma membrane; membrane
Genetic constraint (gnomAD): Missense variants: 182 observed, 249.81 expected, observed/expected ratio (o/e) 0.73, 90% interval 0.64 to 0.82. Synonymous variants: 69 observed, 98.79 expected, observed/expected ratio (o/e) 0.7, 90% interval 0.57 to 0.85.
Homologues: Paralogues in human: OR2T3 (98% identical), OR2T29 (64% identical), OR2T4 (64% identical), OR2T5 (64% identical), OR2T10 (59% identical), OR2T35 (58% identical), OR2T2 (58% identical), OR2T27 (55% identical), OR2T11 (54% identical), OR2T1 (51% identical), OR2T33 (49% identical), OR2T8 (48% identical), and 80 more.